ACVRL1 (activin A receptor like type 1)
Diseases named in the same sentence as ACVRL1 in open-access papers (continued):
Sharing a sentence is not in itself a finding about the gene and the disease.
hereditary hemorrhagic telangiectasia (continued). "AVM is also a component of several hereditary disorders, like hereditary hemorrhagic telangiectasia (HHT, also known as Osler–Weber–Rendu disease), Wyburn–Mason syndrome, and Sturge–Weber syndrome characterized by mutations of endoglin (ENG) or Alk1 (ACVRL1)." (PMID 32677965, 2020). "Hereditary hemorrhagic telangiectasia (HHT), a rare autosomal dominant disease mostly caused by mutations in three known genes (ENG, ACVRL1, and SMAD4), is characterized by the development of vascular malformations (VMs)." (PMID 32842615, 2020). "Follow-up genetic testing for hereditary hemorrhagic telangiectasia (HHT) by ACVRL1 and ENG gene sequencing and duplication/deletion analysis was negative." (PMID 25379312, 2014). "More rarely, mutations in activin receptor like kinase type 1 (ACVRL1 or ALK1) or endoglin genes, also coding for members of the TGF-ß signaling family, have been identified in patients with PAH, predominantly with coexistent hereditary hemorrhagic telangiectasia." (PMID 23829793, 2013). "Hereditary hemorrhagic telangiectasia (HHT) is an autosomal dominant disorder of angiodysplasia, affecting 1 in 5–8,000 people, most commonly caused by mutations in ENG or ALK1/ACVRL1 gene." (PMID 23710379, 2013). "Hereditary hemorrhagic telangiectasia (HHT) is an autosomal dominant vascular disorder caused by pathogenic variants in genes within the transforming growth factor beta (TGF-β) signaling pathway, such as ACVRL1, leading to haploinsufficiency." (PMID 40160294, 2025). "Hereditary Hemorrhagic Telangiectasia (HHT) is an autosomal-dominant genetic disorder involving defects in two predominant genes known as endoglin (ENG; HHT-1) and activin receptor-like kinase 1 (ACVRL1/ALK1; HHT-2)." (PMID 35665360, 2022). "Hereditary Hemorrhagic Telangiectasia (HHT) is an autosomal dominant disorder caused, in more than 80% of cases, by mutations of either the endoglin (ENG) or the activin A receptor-like type 1 (ACVRL1) gene." (PMID 35628811, 2022). "Hereditary Hemorrhagic Telangiectasia (HHT) is an autosomal dominant vascular dysplasia caused by mutations in genes involved in the TGFβ-BMP receptor signaling pathway: ENG (HHT type 1), ACVRL1 (HHT type 2) and MADH4 (HHT overlap syndrome with Juvenile Polyposis)." (PMID 32032395, 2020). "In addition, mutations of the genes ACVRL1 and ENG, encoding the co-receptor endoglin, are responsible of the Rendu-Osler syndrome also known as hereditary hemorrhagic telangiectasia (HHT)." (PMID 30165893, 2018). "Two other genes, ACVRL1 and ENG, which also encode receptors belonging to the TGF-β superfamily, have been more recently identified in PAH accompanying hereditary hemorrhagic telangiectasias (HHT)." (PMID 29743074, 2018). "The observation of the development of PAH in patients displaying hereditary hemorrhagic telangiectasia (HHT), an autosomal dominant vascular dysplasia, allowed us to identify two other PAH predisposing genes: ACVRL1 (Activin A receptor type II-like kinase 1) and ENG (endoglin) genes." (PMID 23829793, 2013). "These entities are often sporadic but are found in association with variants of the RASA1 and EPHB4 genes (capillary malformation–arteriovenous malformation, CMAVM; OMIM #608354) or ACVRL1, ENG, and SMAD4 genes (hereditary hemorrhagic telangiectasia, HHT; OMIM #187300)." (PMID 40259928, 2025).
pulmonary arterial hypertension (29 papers, 2014 to 2025). Pulmonary arterial hypertension (PAH) is a group of diseases characterized by mean pulmonary artery pressure >20 mmHg and elevated pulmonary arterial resistance leading to right heart failure. "An earlier study investigating kindreds with HHT and pulmonary hypertension characterized eight missense mutations of ACVRL1." (PMID 40160294, 2025). "Genetic testing confirmed an ACVRL1 mutation, while an echocardiogram and right heart catheterization confirmed pulmonary arterial hypertension." (PMID 35232468, 2022). "Most of ACVRL1 mutations found in pulmonary arterial hypertension are the same mutations described in HHT which result in a loss of function." (PMID 34702814, 2021). "Although rare, mutations in the ACVRL1 gene were identified in a subset of pulmonary arterial hypertension patients who also develop hereditary hemorrhagic telangiectasia." (PMID 30272025, 2018). "Pulmonary arterial hypertension (PAH) can be discovered in patients who have a loss of function mutation of activin A receptor-like type 1 (ACVRL1) gene, a bone morphogenetic protein (BMP) type 1 receptor." (PMID 31380118, 2019). "The test results were positive for a heterozygous pathogenic variant in the ACVRL1 gene, a gene associated with HHT and pulmonary arterial hypertension (PAH)." (PMID 39314615, 2024). "Eng+/– and Acvrl1+/– mice also develop with age signs of pulmonary arterial hypertension attributable to eNOS-derived ROS, which was preventable by antioxidant treatment." (PMID 25763011, 2015). "Mutations within ACVRL1 and MADH4 may be associated with pulmonary hypertension, while basal cell carcinoma was described in RASA1 mutations." (PMID 33807613, 2021). "In addition, our patient had pulmonary hypertension (PH) that is commonly associated with ACVRL1 mutations, revealing her phenotype was not consistent with isolated ENG genetic mutations." (PMID 36440054, 2022). "Previous studies have shown that TGF-β pathway plays an important role in PAH by regulating pulmonary vascular remodeling, variation of several TGF-β family receptor members, such as ACVRL1, ENG and SMAD9, are pathogenic genes of hereditary pulmonary arterial hypertension patients." (PMID 34310344, 2021). "ACVRL1 belongs to the family of TGF-β I receptors, and its abnormal changes significantly affect the regulation of the TGF-β pathway, contributing to the development of pulmonary hypertension." (PMID 35185890, 2022). "In this study, we analyzed 7 PAH-causing genes including BMPR2, ACVRL1, ENG, SMAD9, CAV1, KCNK3, and CBLN2 in 49 CTEPH patients and 17 patients recovered from pulmonary embolism (PE) but without pulmonary hypertension(PH)." (PMID 26820968, 2016). "Additionally, heritable pulmonary arterial hypertension (PAH) due to proliferative vasculopathy is a distinct pathological process that has been observed in HHT, particularly in individuals with ACVRL1-related HHT." (PMID 40160294, 2025).
juvenile polyposis (21 papers, 2010 to 2025). "HHT is transmitted as an autosomal dominant trait due to a single mutation in either ENG encoding endoglin (HHT type 1); ACVRL1 encoding ALK-1 (HHT type 2) or SMAD4 (HHT in association with juvenile polyposis)." (PMID 20701797, 2010). "Endoglin (ENG), activin A receptor type II-like 1 (ACVRL1/ALK1), and SMAD4 mutations cause HHT1 (OMIM 187300), HHT2 (OMIM 600376), and the combined Juvenile Polyposis/HHT (JP/HHT) syndrome (OMIM 175050), respectively." (PMID 39062925, 2024). "Three genetic mutations have been identified: ENG (HHT1); ACVRL1 (HHT2); and more rarely, SMAD4 (found in HHT associated with juvenile polyposis syndrome), however several hundred different mutations have been described." (PMID 31174568, 2019). "One patient with mutations in both ENG and ACVRL1 genes was identified, as were two SMAD4-mutated patients suffering from the overlapping juvenile polyposis-HHT syndrome." (PMID 30251589, 2018). "Mutations in three genes have been found to be responsible for HHT: the endoglin (ENG) gene on chromosome 9, the activin-receptor-like kinase 1 (ACVRL1) gene on chromosome 12, and the SMAD4 gene on chromosome 18 (mutations also lead to juvenile polyposis)." (PMID 24603803, 2014). "Mutations in ENG were identified in 31 patients (55%), mutations in ACVRL1 were identified in 17 patients (30%), and one patient had a mutation in SMAD4 and presented with juvenile polyposis." (PMID 24603803, 2014). "Pathogenic variants in the ENG and ACVRL1 genes result in different HHT types, commonly referred to as HHT1 and HHT2, respectively Pathogenic variants in the SMAD4 gene give rise to a combined syndrome of HHT and juvenile polyposis (JP): the JP-HHT syndrome." (PMID 35628811, 2022). "The majority (>85%) of HHT patients are heterozygous for loss of function (LOF) mutations in the endoglin (ENG, HHT1) or activin A receptor like type 1 (ALK1, HHT2) genes, whilst a minority (∼5%) carry mutations in the SMAD4 gene and show a combined juvenile polyposis and HHT phenotype." (PMID 36250069, 2022). "Endoglin (ENG, chromosome 9q34), Activin A receptor type II-like 1 (ACVRL1/ACVRL1/ALK1, chromosome 12q13), and MADH4/SMAD4 (chromosome 18q21) mutations cause HHT1 (OMIM 187300), HHT2 (OMIM 600376), and the combined Juvenile Polyposis/HHT (JP/HHT) syndrome (OMIM 175050), respectively." (PMID 28231770, 2017). "Endoglin (ENG, chromosome 9q34), activin A receptor type II-like 1 (ACVRL1/ALK1, chromosome 12q13), and SMAD4 (chromosome 18q21) mutations cause HHT1 (OMIM 187300), HHT2 (OMIM 600376), and the combined Juvenile Polyposis/HHT (JP/HHT) syndrome (OMIM 175050), respectively." (PMID 25674101, 2015). "Genetic diagnosis is based on the identification of a mutation in the transforming growth factor-beta (TGF-β) signaling pathway genes: Endoglin (ENG), activin receptor-like kinase 1 (ACVRL 1), or SMAD4 characterized by the juvenile polyposis syndrome (JPS) usually associated with HHT." (PMID 31971937, 2020). "Single mutations are detected in Endoglin (ENG; HHT1) (MIM # 131195), Activin Receptor-Like Kinase 1 (ACVRL1/ALK1; HHT2) (MIM # 601284), or MADH4/SMAD4 (JHPT, a combined syndrome of juvenile polyposis and HHT)." (PMID 26176610, 2015). "In 90% of patients with a definite clinical diagnosis of HHT, a mutation is identified in one of these three genes: endoglin (ENG, HHT type 1), activin receptor-like kinase-1 (ACVRL1, HHT type 2), and Mothers against decapentaplegic homolog 4 (SMAD4, juvenile polyposis–HHT overlap syndrome)." (PMID 39597796, 2024). "In 96% of patients with a definite clinical diagnosis of HHT, a mutation is identified in one of these 3 genes: endoglin (ENG, HHT type 1), activin receptor-like kinase-1 (ACVRL1, HHT type 2), and Mothers against decapentaplegic homolog 4 (SMAD4, juvenile polyposis–HHT overlap syndrome)." (PMID 38492037, 2024).
arteriovenous malformations (17 papers, 2012 to 2025). "Patients with hereditary hemorrhagic telangiectasia (HHT) have arteriovenous malformations (AVMs) with genetic mutations involving the activin-A receptor like type 1 (ACVRL1 or ALK1) and endoglin (ENG)." (PMID 35380991, 2022). "Using the neonatal retinal plexus to examine angiogenesis, we observed that loss of endothelial Acvrl1 led to venous enlargement, vascular hyperbranching and arteriovenous malformations." (PMID 24896812, 2014). "Our goal was to examine the role of Acvrl1 in vascular endothelial cells during vascular development and to determine whether loss of endothelial Acvrl1 leads to arteriovenous malformations." (PMID 24896812, 2014). "Mutations in endoglin (ENG) and activin receptor-like kinase 1 (ACVRL1) (encoding ALK1) have been linked to a human vascular disorder hereditary hemorrhagic telangiectasia (HHT1 and HHT2, respectively), often resulting in arteriovenous malformations (AVM)." (PMID 32183218, 2020). "Mutations in endoglin (ENG) and activin receptor-like kinase 1 (ACVRL1) genes are responsible for HHT1 and HHT2 and are associated with arteriovenous malformations." (PMID 25763011, 2015). "The majority of patients carry mutations in either Endoglin (ENG) or ACVRL1 (also known as ALK1) genes, and the disease is characterized by arteriovenous malformations and persistent haemorrhage." (PMID 24896812, 2014). "Causative mutations in one of several genes, most commonly endoglin (ENG) or activin receptor-like kinase 1 (ACVRL1) and less commonly SMAD4, lead to the characteristic HHT lesions—large vessel arteriovenous malformations (AVMs) and/or small vessel telangiectases." (PMID 30191360, 2019). "Because RASA1 mutations have previously been associated with capillary and arteriovenous malformations similar to the HHT phenotype, and because no variants were identified in the ENG, ACVRL1, or SMAD4 genes, the RASA1 variant was assumed to be the causative mutation for this sample." (PMID 24268183, 2013).
Telangiectasia (14 papers, 2012 to 2025). Telangiectasias refer to small dilated blood vessels located near the surface of the skin or mucous membranes, measuring between 0.5 and 1 millimeter in diameter. "Heterozygous ACVRL1 mutations generally cause the classic telangiectases and AVMs of HHT, but in rare cases can also cause PAH." (PMID 33834622, 2021). "The study included description of the clinical features, documentation of the extent of telangiectasia, and identification of a new mutation in the ACVRL1 gene." (PMID 23460919, 2013). "Somatic mosaic lesion-specific ACVRL1 variants were identified in four hepatic AVM samples and in one telangiectasia." (PMID 41162588, 2025). "We identified a pathogenic somatic second hit from at least one telangiectasia sample from every individual with a germline mutation in ACVRL1, and none of the individuals with a germline mutation in ENG." (PMID 39062925, 2024). "In stark contrast, telangiectases seen in HHT patients with ACVRL1, ENG, or SMAD4 mutations are overwhelmingly punctate (not spidery) and typically occur on the lips and oral cavity, not other aspects of the face." (PMID 33834622, 2021). "Mutations of ACVRL1, the gene for ALK-1, are associated with the appearance of hereditary hemorrhagic telangiectasia type 2, a vascular dysplasia characterized by telangiectasias in the skin, nose bleeds and arteriovenous malformations in several organs, mainly in the liver." (PMID 26398936, 2015). "Hereditary Haemorrhagic Telangiectasia (HHT), Activin A Receptor Like Type 1 (ACVRL1), Mothers Against Decapentaplegic homolog 4 (SMAD4), Phosphatase and Tensin homolog (PTEN), Ras p21 protein activator 1 (RASA1), PIK3 CA and Ephrin 4 (EPHB4) testing were all negative for pathogenic mutation." (PMID 40490531, 2025).
vascular malformation (10 papers, 2015 to 2025). A non-neoplastic disorder that is the result of defects of vascular morphogenesis. "Recently, somatic mutations in ACVRL1 causing biallelic loss-of-function were found in liver vascular malformations and a skin telangiectasis from one patient, providing further evidence of biallelic HHT gene inactivation in HHT-associated vascular malformations." (PMID 40648852, 2025). "HHT is a rare genetic disease leading to vascular malformations, caused by pathogenic variants in ENG or ACVRL1, the two major genes." (PMID 36059817, 2022). "In this way, somatic mutations would increase the number of ECs that are null for endoglin (in HHT1) or null for ACVRL1 (in HHT2) and following exposure to angiogenic or inflammatory signals these “null” ECs would be associated with vascular malformations." (PMID 25741358, 2015). "First, we performed manual analysis and variant calling of the sequencing data for the genes known to cause HHT (ACVRL1, ENG, GDF2, SMAD4) or vascular malformation syndromes with similar phenotypes (EPHB4, RASA1), as well as PIK3CA, which has been shown to modify vascular malformation phenotypes." (PMID 39062925, 2024). "In addition, animal models with systemic or endothelial-specific deletion of Eng, Acvrl1, or Smad4 in adulthood lead to vascular malformations compatible with an HHT phenotype." (PMID 33167572, 2020). "For example, the ACVRL1c.314-35A>G common variant was shown to be associated with sporadic brain AVMs, and also subsequently with PAVMs as well as vascular malformations overall in patients with ENG mutations, but not in patients with ACVRL1 mutations." (PMID 33167572, 2020). "Genetic analyses of ACVRL1, ENG, and SMAD4 (in addition to EPHB4 and RASA1) are considered reasonable in all cases of high-flow intracerebral vascular malformations regardless of other HHT signs." (PMID 40259928, 2025).
breast carcinoma (7 papers, 2019 to 2026). "Neumorous studies have reported elevated ACVRL1 expression in certain tumours such as hepatocellular carcinoma, breast cancer, where it is associated with aberrant angiogenesis and tumour progression." (PMID 41579221, 2026). "The present study showed BMP8B was significantly increased in breast tumours, while BMP6 and ACVRL1 were decreased in breast cancer tissues." (PMID 37333824, 2023). "Based on our previous observations that ACVRL1 expression is associated with immune features of the TME in a series of human solid malignancies, we confirmed the generality of this regulation in breast cancer." (PMID 39808498, 2025). "Reduced levels of ACVRL1 were seen in both cohorts of breast cancer." (PMID 37333824, 2023). "ACVRL1 would be a key BMP receptor with breast cancer angiogenesis and lymphangiogenesis." (PMID 37333824, 2023). "ACVRL1 induced metastasis and angiogenesis in mouse models and further demonstrated that ACVRL1 was involved in cell dissemination and tumour progression of breast cancer." (PMID 37333824, 2023). "Furthermore, overexpressed ACVRL1 is a factor of breast cancer patients with poor prognosis." (PMID 37333824, 2023). "Breast cancer patients exhibiting an ACVRL1hi TAM signature have significantly shorter survival, and ACVRL1 has been identified as an effector target for adjuvant anti-angiogenic immunotherapy in metastatic models." (PMID 41417432, 2025). "Both BMP1 receptor and ACVRL1 are members of the BMP receptors, which may be important in breast cancer promotion and progression." (PMID 33462336, 2021). "The expressions of PCDH12, SLIT3, ACVRL1 and DLL4 not merely relate to the type and proportion of immune cells, but also contribute to the prognosis of breast cancer." (PMID 35953532, 2022).
anemia (6 papers, 2014 to 2025). A reduction in the number of red blood cells, the amount of hemoglobin, and/or the volume of packed red blood cells. "The neonate was confirmed to be free of the ACVRL1 gene variant, and her PH resulted from impaired placental perfusion and adverse intrauterine environment secondary to severe maternal PH and anemia." (PMID 40933708, 2025). "It has been related to ACVRL1 gene mutation, older age and the presence of cirrhosis or iron-deficiency anemia." (PMID 39709450, 2024). "Patients with ACVRL1 variants developed symptomatic liver disease and anemia more usually than ENG patients." (PMID 32503579, 2020). "Patients with ACVRL1 variants had a higher cardiac index (2.62 vs 3.46), higher levels of hepatic functional blood tests, and anemia (28.5% vs 56.7%) more often than ENG patients." (PMID 32503579, 2020). "Endothelial-specific depletion of Acvrl1 in pups also led to pulmonary haemorrhage, but in adult mice resulted in caecal haemorrhage and fatal anaemia." (PMID 24896812, 2014). "While ENG patients require vigilant screening for pulmonary AVMs, ACVRL1 patients may benefit from close monitoring of epistaxis severity, anemia, and lipid metabolism." (PMID 40648782, 2025). "In our study three out of five patients had ACVRL1 mutation (one had ENG mutation and one was not tested), only one had anemia and the mean age was not comparable due to matching." (PMID 39709450, 2024).
epistaxis (5 papers, 2017 to 2025). Bleeding from the nose. "Compared to controls, RHC PH cohort patients had fewer epistaxis episodes (p = 0.0196), more frequent and significant hepatic vascular involvement (p = 0.0008) and more frequently carried the ACVRL1 mutation (p = 0.0264)." (PMID 28981519, 2017). "As previously reported, epistaxis was the most common symptom found in almost all patients with ENG- or ACVRL1-HHT after 12 years of age." (PMID 34872578, 2021). "Epistaxis is the most common (> 90%) manifestation in patients with both ENG and ACVRL1 mutations, although patients with ENG mutations are believed to have onset of epistaxis at a younger age." (PMID 32660636, 2020).